ENSG00000285253 (novel protein)
Gene: Protein-coding gene on chromosome 15 (56,652,488 to 56,918,571, reverse strand). Ensembl gene ENSG00000285253.
Genetic constraint (gnomAD): Loss-of-function variants: 21 observed, 56.94 expected, observed/expected ratio (o/e) 0.37, 90% interval 0.26 to 0.53. Missense variants: 629 observed, 706.44 expected, observed/expected ratio (o/e) 0.89, 90% interval 0.83 to 0.95. Synonymous variants: 237 observed, 229.04 expected, observed/expected ratio (o/e) 1.03, 90% interval 0.93 to 1.15.